A2M (alpha-2-macroglobulin)
Description:
Is able to inhibit all four classes of proteinases by a unique 'trapping' mechanism. This protein has a peptide stretch, called the 'bait region' which contains specific cleavage sites for different proteinases. When a proteinase cleaves the bait region, a conformational change is induced in the protein which traps the proteinase. The entrapped enzyme remains active against low molecular weight substrates (activity against high molecular weight substrates is greatly reduced). Following cleavage in the bait region, a thioester bond is hydrolyzed and mediates the covalent binding of the protein to the proteinase.
Synonyms: CPAMD5; FWP007; S863-7; A2MD
Tractability: Small molecule: an approved drug acts on it; it has a binding pocket of medium quality. Antibody: UniProt places it where antibodies can reach, with high confidence; its Gene Ontology location is reachable by antibodies, with high confidence; UniProt predicts a signal peptide or a membrane-spanning region. PROTAC: its protein half-life has been measured.
Gene: Protein-coding gene on chromosome 12 (9,067,664 to 9,116,229, reverse strand). Ensembl gene ENSG00000175899.
Subcellular location: Secreted
Pathways (Reactome):
Extracellular matrix organization: Degradation of the extracellular matrix
Hemostasis: Platelet degranulation
Immune System: Regulation of FXIIa and plasma kallikrein activity
Transport of small molecules: HDL assembly
Gene Ontology:
Molecular function: calcium-dependent protein binding; endopeptidase inhibitor activity; enzyme binding; growth factor binding; interleukin-1 binding; interleukin-8 binding; protease binding; protein binding; serine-type endopeptidase inhibitor activity; signaling receptor binding; tumor necrosis factor binding
Biological process: negative regulation of complement activation, lectin pathway
Cellular component: blood microparticle; extracellular exosome; extracellular matrix; extracellular region; platelet alpha granule lumen
Genetic constraint (gnomAD): Loss-of-function variants: 95 observed, 147.24 expected, observed/expected ratio (o/e) 0.65, 90% interval 0.55 to 0.76. The upper end of that interval is the gene's LOEUF score, 0.76, which puts it in group 3 of 6, group 1 being the genes least tolerant of losing a copy. Missense variants: 1,328 observed, 1,633.3 expected, observed/expected ratio (o/e) 0.81, 90% interval 0.78 to 0.85. Synonymous variants: 541 observed, 625.24 expected, observed/expected ratio (o/e) 0.87, 90% interval 0.81 to 0.93.
Homologues: Orthologues: chimpanzee A2M (99% identical), dog A2M (80% identical), rabbit A2M (78% identical), pig A2M (76% identical), rat A2m (73% identical), guinea pig A2M (73% identical), mouse A2m (72% identical), tropical clawed frog a2m (50% identical), tropical clawed frog pzp (49% identical), tropical clawed frog ovos2 (36% identical), Drosophila melanogaster Tep2 (26% identical), Caenorhabditis elegans tep-1 (26% identical), and 3 more. Paralogues in human: PZP (72% identical), A2ML1 (40% identical), CD109 (28% identical), CPAMD8 (28% identical), C3 (24% identical), C4A (23% identical), C4B (23% identical), C5 (21% identical).
Diseases named in the same sentence as A2M in open-access papers:
A2M is named in the same sentence as 197 diseases in open-access papers, as found by Europe PMC text mining. Sharing a sentence is not in itself a finding about the gene and the disease. The quoted sentences say what the papers report.
liver fibrosis (19 papers, 2010 to 2025). "Well-established diagnostic biomarkers for liver fibrosis, including alpha-2-macroglobulin (A2M) and von Willebrand factor (VWF), have significant drawbacks, such as insufficient specificity and individual variability." (PMID 40943308, 2025). "The score is composed of six biomarkers (CA 19-9, age, alpha-2- macroglobulin, total bilirubin, platelet count & albumin), which are previously known to have significant diagnostic values of staging hepatic fibrosis and progression of liver disease in general." (PMID 24046790, 2013). "This is in line not only with the role of A2M as a regulator of the extracellular matrix and the well-known positive association of A2M in the extracellular matrix of liver fibrosis, but also with the early damage of proteins associated with the very early presence of T2DM." (PMID 35327501, 2022). "Furthermore, A2M alterations have been previously reported in other diseases besides AD, such as chronic lung diseases, liver fibrosis and are linked to patients with congenital antithrombin deficiency." (PMID 35456941, 2022). "The induction of liver fibrosis by CCl4 led to a significant (P < 0.05) increase in the serum levels of alpha-2-macroglobulin and a significant (P < 0.05) decrease in APOA1 in serum after 5 and 9 weeks of CCl4 treatment compared to the control group." (PMID 35881285, 2022). "This, as well as exposure to other bioactive molecules such as alpha-2 macroglobulin (A2M), tilts the balance towards fibrogenesis, which is a key link in the development of liver fibrosis in NAFLD." (PMID 34831201, 2021). "Multivariate analysis showed that the most relevant collection of biomarkers for prediction of stage of hepatic fibrosis is: CA 19-9, age, alpha-2- macroglobulin, total bilirubin, platelet count & albumin." (PMID 24046790, 2013). "Multiple regression analysis for prediction of the stage of hepatic fibrosis indicated that CA 19-9, age, alpha-2-macroglobulin, total bilirubin, platelet count and albumin were the most relevant biomarkers related to the stage of hepatic fibrosis." (PMID 24046790, 2013). "This study not only reveals three putative biomarkers of liver fibrosis (A2M, VDBP and ApoAI) but also proves the differential expressions of those markers in different stages of fibrosis." (PMID 20630109, 2010). "In summary, this study not only reveals three putative biomarkers of liver fibrosis (A2M, VDBP and ApoAI) but also proves the differential expressions in different stages of fibrosis." (PMID 20630109, 2010). "In the present study, downregulation of A2M might reduce liver fibrosis, suggesting that A2M is a novel biomarker target of sericin." (PMID 38443583, 2024). "The CKG automatically reproduced our previous results showing dysregulation of proteins involved in immune system regulation and inflammation, such as C7, JCHAIN, PIGR and A2M, a known marker of liver fibrosis for which CKG reported 14 publications, confirming this connection." (PMID 35102292, 2022). "A2M, which was already found to be upregulated in our previous study focusing on MA treatment, has previously been used as a serum test marker for patients suffering from moderate or advanced hepatic fibrosis." (PMID 35328776, 2022). "In patients with non-alcoholic fatty liver disease (NAFLD) with or without type 2 diabetes mellitus (T2DM), alpha-2 macroglobulin (A2M), apolipoprotein A1 (ApoA1), and haptoglobin are associated with the risk of liver fibrosis, inflammation (NASH), and COVID-19." (PMID 35327501, 2022). "Interestingly, alpha 2 macroglobulin and haptoglobin are known to act as markers of fibrosis in the liver, and together with ApoA-I and some key liver enzymes are being used in algorithms that stage liver fibrosis and predict its progression." (PMID 29849043, 2018).
liver fibrosis (continued). "Both significant and advanced hepatic fibrosis could be predicted by a novel panel of serum biomarkers (Egy-Score) composed of CA 19-9, age, alpha-2- macroglobulin, total bilirubin, albumin and platelet count (in a regression equation) with good sensitivity and specificity." (PMID 24046790, 2013). "Alpha 2 macroglobulin (A2M) is up regulated whereas vitamin D binding protein (VDBP) and apolipoprotein AI (ApoAI) are down regulated in hepatic fibrosis serum." (PMID 20630109, 2010). "MicroRNA-34a (miR-34a) represents a marker for steatosis, inflammation, and hepatocyte ballooning; alpha-2 macroglobulin and YKL40 represent markers for hepatic fibrosis, and YKL40 is also involved in inflammation and tissue remodeling in response to endothelial dysfunction." (PMID 32933184, 2020).
Alzheimer disease (16 papers, 2008 to 2025). A progressive, neurodegenerative disease characterized by loss of function and death of nerve cells in several areas of the brain leading to loss of cognitive function such as memory and language. "Because clusterin and α2M are both associated with protein deposition diseases such as Alzheimer's disease, prion disease, and atherosclerosis, both chaperones have similar physiological roles." (PMID 36977730, 2023). "In fact, alpha-2-macroglobulin has been associated with an almost 3-fold greater risk of Alzheimer's disease." (PMID 35502212, 2022). "For example, α2M can stabilise and facilitate the clearance of the Alzheimer's disease-associated amyloid beta (Aβ) peptide." (PMID 31428227, 2019). "In part, this stems from early reports that polymorphisms in α2M are associated with increased risk of Alzheimer's disease in some populations." (PMID 31428227, 2019). "Of the studies reporting an association between mutation in α2M and risk of Alzheimer's disease, one study has reported that there is a synergistic effect between polymorphisms in α2M and myeloperoxidase and an increased risk of Alzheimer's disease." (PMID 31428227, 2019). "A2M is implicated in Alzheimer’s disease (AD) and mediates the clearance and degradation of β-amyloid deposits." (PMID 24651125, 2014). "One of these excessive proinflammatory cytokines, IL-6, is implicated in improper beta-amyloid processing during Alzheimer's disease (AD) due to its effects on alpha-2-macroglobulin (A2M)." (PMID 18171484, 2008). "In addition, A2M has been implicated in Alzheimer's disease due to its ability to degrade β-amyloid deposition." (PMID 40421055, 2025). "For example, apolipoprotein E (ApoE) is an endogenous ligand of α2M in blood plasma, and the binding of α2M to the ε4 isoform (the strongest known genetic risk factor for Alzheimer's disease) is much less compared to the binding of α2M to the ε2 and ε3 ApoE isoforms." (PMID 31428227, 2019). "A2M is a component of Lewy bodies, a hallmark of the neuropathology of PD and is considered a candidate gene for Alzheimer disease; however, the association between SNPs in A2M and risk for PD or AD remains unknown with positive and negative reports of association." (PMID 24073418, 2013). "Furthermore, the decline in alpha-2-macroglobulin with increasing age could be explained by the genetic association between alpha-2-macroglobulin polymorphisms in Alzheimer's disease." (PMID 21365000, 2011). "A2M is known to mediate the clearance of amyloid-beta, a protein product commonly elevated in individuals with Alzheimer’s disease." (PMID 32787845, 2020). "There is strong evidence that native α2M can inhibit the aggregation and toxicity of Aβ peptide (the major constituent of extracellular plaques in Alzheimer's disease)." (PMID 31428227, 2019). "Similar to α2M, there are conflicting reports regarding an association between polymorphisms in LRP1 and the risk of Alzheimer's disease." (PMID 31428227, 2019). "α2M is found colocalised with the Aβ peptide in the brain in Alzheimer's disease, which supports the idea that the LRP1-mediated clearance of α2M-Aβ complexes is impaired or overwhelmed." (PMID 31428227, 2019). "It has recently been reported that serum α2M is elevated in men with preclinical Alzheimer's disease, which potentially represents a general response to neuronal injury." (PMID 31428227, 2019). "Many studies have suggested that the alpha-2-macroglobulin (A2M) gene may be involved in the pathogenesis of Alzheimer's disease (AD)." (PMID 36698894, 2022). "Interest in the role of α2M in Alzheimer's disease spans several decades." (PMID 31428227, 2019). "A2M has a well-characterized role in Alzheimer’s disease and aging in multiple species." (PMID 30978202, 2019).
Alzheimer disease (continued). "Alternatively, it is possible that neither genetic predisposition nor Alpha-2-macroglobulin quantity contribute towards the pathology of Alzheimer's disease, but rather differences in post-translational modification of this protein." (PMID 21365000, 2011). "Given that the accumulation of the Aβ peptide in the brain in Alzheimer's disease appears to be the result of a defect in clearance, rather than elevated production of the peptide, it is important to understand the contribution of α2M to the clearance of the Aβ peptide in greater detail." (PMID 31428227, 2019). "Specifically, the underlying assumption is that the (5 base pair intronic) deletion in the Alpha-2-macroglobulin gene may affect the functionality and quantity of the resultant Alpha-2-macroglobulin protein in circulation, therefore contributing to Alzheimer's disease pathology." (PMID 21365000, 2011). "Roles for α2M in preventing or promoting neurodegeneration independent of Alzheimer's disease are less clear." (PMID 31428227, 2019).
diabetes (15 papers, 2011 to 2025). "Another protein connected to diabetes, Alpha-2-macroglobulin (A2M), was one of the proteins shown to be elevated in both the AD and T2DM groups relative to the control group in studies." (PMID 39274269, 2024). "Among them, SERPINA1, A2M, and AGT fluctuations are known to be associated with embryogenesis and pregnancy condition and long-term diabetes mellitus." (PMID 33184417, 2020). "Alpha-2 macroglobulin protein has been previously found to be involved in a number of different diseases, including nephrotic syndrome, diabetes, and liver cirrhosis." (PMID 29761050, 2018). "Several studies have suggested a role for α2M in diabetes and more recently in DKD." (PMID 34572299, 2021). "Indeed, a common comorbidity of HFE-HH is type 2 diabetes, which is closely associated with impaired haemorheology, due in part, to increased fibrinogen and alpha 2-macroglobulin; our patients were reported free of diabetes." (PMID 26741993, 2016). "A2m, a cytokine transporter induced by interleukin and predominantly expressed in blood vessel walls and the retinal pigment epithelium in the retina has also been described as systemically elevated in diabetes patients." (PMID 21575160, 2011). "Chronically elevated alpha-2-macroglobulin (A2MG) in the blood has been correlated with diabetes and the HbA1c profile; however, no systematic review has been conducted to evaluate the association of A2MG salivary levels and glycemia or HbA1c levels in diabetes mellitus type 2 (DM2) patients." (PMID 36102452, 2022). "The detection of fibrinogen molecules, as well as alpha-2 macroglobulin in PDR vitreous, confirmed the relevance of a hypercoagulable state in the pathogenesis of diabetes-related severe damage." (PMID 34216255, 2021).
osteoarthritis (11 papers, 2017 to 2024). A noninflammatory degenerative joint disease occurring chiefly in older persons, characterized by degeneration of the articular cartilage, hypertrophy of bone at the margins and changes in the synovial membrane. "Previous research has indicated that miR-146b plays a role in promoting osteoarthritis, a condition associated with aging, by inhibiting the alpha-2-macroglobulin expression." (PMID 37685971, 2023). "Especially when people realized the broad-spectrum anti-protease effect of α2M, it was more fully applied in motor system diseases such as acromion bursitis, tendinitis, osteoarthritis, and intervertebral disc disease." (PMID 36987418, 2023). "Direct injection of α2M into inflamed joints has been shown to have protective effects in a rodent model of osteoarthritis; however, the efficacy and safety of this as a human therapy is not yet known." (PMID 31428227, 2019). "Alpha 2 macroglobulin (A2M), a multi-functional protein in the plasma protease inhibitor class, regulates proinflammatory cytokines and the clearance of chondrodestructive enzymes in cases of joint injury and osteoarthritis (OA)." (PMID 38406632, 2024). "α2-Macroglobulin (α2M) is important to chondral protection in post-traumatic osteoarthritis." (PMID 36133821, 2022). "α2M was then identified as a key regulator of several cartilage degenerating factors and intra-articular injections of α2M could ameliorate osteoarthritis progression." (PMID 34268335, 2021). "Our study indicates that miR-146b plays a critical role in the progression of injury-induced osteoarthritis by directly targeting A2M expression to elevate the proteolytic enzyme production and stimulate chondrocytes apoptosis, and miR-146b as well as A2M could be therapeutic targets." (PMID 31422941, 2019). "There were studies showing that A2M played an important role in the function of many immune cells, and TGM2 was involved in several autoimmune diseases such as celiac disease, inflammatory bowel disease, osteoarthritis, and idiopathic inflammatory myopathies." (PMID 35406685, 2022).
Sepsis (11 papers, 2012 to 2025). Sepsis is defined as life-threatening organ dysfunction caused by a dysregulated host response to infection. "Notably, these DEPs including Fads2, Fgb, Cypla2, Cyp2e1, Cfb, Serping1, Fgg, Etnppl, Agt, Hsd3b5, Gnmt, A2m, Pck1, Stat3, Ptpn1, Scd1, Slc2a1, and Uox were key genes in liver sepsis, which maybe associated with inflammation in sepsis." (PMID 37255592, 2023). "We recently reported that levels alpha-2-macroglobulin (A2MG)-containing microparticles are elevated in plasma from patients with sepsis." (PMID 24357647, 2014). "The activated α2M plasma concentration is, however, increased in many disease states including pancreatitis, multiple sclerosis and sepsis." (PMID 23353684, 2013). "To validate our findings, we extended the number of plasma samples for trauma (n = 23) and sepsis patients (n = 23) and performed quantitative ELISA to measure the contents of A2M, IL1F10, SYT13, and TREM1 in these samples at three time points (day 0, 3 and 5)." (PMID 38283341, 2023). "Furthermore, A2M plays a crucial role in the regulation of fibrinolysis and coagulation processes through its inhibition of proteinases, a phenomenon that has been documented in patients with sepsis." (PMID 40243635, 2025). "Thus, alpha-2-macroglobulin expression was suggested as a potential prognostic marker in sepsis." (PMID 33353087, 2020). "In addition, in the cases of sepsis, other protease inhibitors, such as alpha-2-macroglobulin, may also decrease." (PMID 22514695, 2012). "A2M, IL1F10, SYT13, and TREM1 emerge as compelling biomarkers for sepsis and trauma based on their distinct roles in immune response modulation." (PMID 38283341, 2023). "A number of proteins identified as outcome predictors have also been shown to be differentially expressed in sepsis, including SAA1, CRP, SERPINA1, KLKB1, and A2M, indicating a general inflammatory signature rather than specific markers of COVID-19." (PMID 36812516, 2022). "First, one of the key LRP1 ligands, alpha-2-macroglobulin (A2MG), enhances survival during sepsis through a novel mode of interaction between cells that involve plasma membrane-shed vesicles containing large proteins and lipid mediators." (PMID 26031516, 2015). "Moreover, we corroborated the results of the repressed liver metabolic processes and enhanced the immune response in sepsis mice via RT-qPCR targeting the marker genes, such as Acaca, Acacb, Cyp7a1, FGF2, and A2m." (PMID 37512913, 2023). "It is also observed that alpha-2-macroglobulin positive EVs were present in higher amounts in survivors of pneumonia-related sepsis than non-survivors." (PMID 33353087, 2020). "To conclude, our research emphasizes the potential of A2M, IL1F10, SYT13, and TREM1 as a composite set of biomarkers for distinguishing between non-infected trauma and sepsis patients." (PMID 38283341, 2023).